MIR148A (microRNA 148a)
Synonyms: hsa-mir-148; hsa-mir-148a; MIRN148; MIRN148A; mir-148a
Gene: MicroRNA gene on chromosome 7 (25,949,919 to 25,949,986, reverse strand). Ensembl gene ENSG00000199085.
Gene Ontology:
Biological process: miRNA-mediated post-transcriptional gene silencing
Cellular component: RISC complex
Homologues: Orthologues: chimpanzee ptr-mir-148a (100% identical), guinea pig MIR148A (100% identical), pig MIR148A (99% identical), tropical clawed frog xtr-mir-148a (84% identical), zebrafish dre-mir-148 (81% identical), zebrafish dre-mir-152 (74% identical). Paralogues in human: MIR148B (78% identical), MIR152 (74% identical).
Diseases named in the same sentence as MIR148A in open-access papers:
MIR148A is named in the same sentence as 1 disease in open-access papers, as found by Europe PMC text mining. Sharing a sentence is not in itself a finding about the gene and the disease.
MIR148A shares sentences with these, for which no sentence is quoted: Obesity (1 paper).